ACSM3 (acyl-CoA synthetase medium chain family member 3)
Description:
Catalyzes the activation of fatty acids by CoA to produce an acyl-CoA, the first step in fatty acid metabolism. Capable of activating medium-chain fatty acids with a preference for isobutyrate among fatty acids with 2-6 carbon atoms (By similarity).
Synonyms: SAH; SA
Tractability: PROTAC: its protein half-life has been measured.
Gene: Protein-coding gene on chromosome 16 (20,610,243 to 20,797,843, forward strand). Ensembl gene ENSG00000005187.
Subcellular location: Mitochondrion; Mitochondrion matrix
Pathways (Reactome):
Metabolism: Beta oxidation of butanoyl-CoA to acetyl-CoA
Gene Ontology:
Molecular function: medium-chain fatty acid-CoA ligase activity; 2-methylbutanoate-CoA ligase activity; fatty acid ligase activity; fatty-acyl-CoA synthase activity; propionate-CoA ligase activity; CoA-ligase activity; propionate CoA-transferase activity; short-chain fatty acid-CoA ligase activity
Biological process: acyl-CoA metabolic process; cholesterol homeostasis; fatty acid biosynthetic process; regulation of blood pressure
Cellular component: mitochondrion; mitochondrial matrix
Genetic constraint (gnomAD): Loss-of-function variants: 57 observed, 71.15 expected, observed/expected ratio (o/e) 0.8, 90% interval 0.65 to 1. The upper end of that interval is the gene's LOEUF score, 1, which puts it in group 4 of 6, group 1 being the genes least tolerant of losing a copy. Missense variants: 588 observed, 665.42 expected, observed/expected ratio (o/e) 0.88, 90% interval 0.82 to 0.95. Synonymous variants: 198 observed, 234.43 expected, observed/expected ratio (o/e) 0.84, 90% interval 0.75 to 0.95.
Homologues: Orthologues: chimpanzee ACSM3 (99% identical), macaque ACSM3 (91% identical), rabbit ACSM3 (88% identical), dog ACSM3 (87% identical), pig ACSM3 (86% identical), guinea pig ACSM3 (85% identical), mouse Acsm3 (85% identical), rat Acsm3 (84% identical), tropical clawed frog acsm3 (66% identical), zebrafish acsm3 (63% identical), Caenorhabditis elegans acs-2 (19% identical), Caenorhabditis elegans acs-1 (19% identical). Paralogues in human: ACSM4 (59% identical), ACSM5 (58% identical), ACSM2A (54% identical), ACSM2B (53% identical), ACSM1 (51% identical), ACSM6 (37% identical), ACSS2 (28% identical), ACSS1 (27% identical), ACSS3 (25% identical), ACSF2 (20% identical), ACSF3 (20% identical), AACS (19% identical), and 1 more.
Diseases named in the same sentence as ACSM3 in open-access papers:
ACSM3 is named in the same sentence as 38 diseases in open-access papers, as found by Europe PMC text mining. Sharing a sentence is not in itself a finding about the gene and the disease. The quoted sentences say what the papers report.
hepatocellular carcinoma (6 papers, 2018 to 2023). A malignant tumor that arises from hepatocytes. "The expression of ACSM3 is significantly reduced in hepatocellular carcinoma tissues and is associated with the late stage and poor survival rates of hepatocellular carcinoma." (PMID 37426827, 2023). "Potentially interesting information about the signaling and metabolic functions of ACSM3 comes from studies of hepatocellular carcinoma, where its downregulation is associated with poor prognosis." (PMID 33923085, 2021). "Overexpression of ACSM3 is able to weaken the migration and invasion of hepatocellular carcinoma cells." (PMID 37426827, 2023). "And ACSM3 was found to be correlated with poor survival in advanced hepatocellular carcinoma." (PMID 34322485, 2021). "The expression of ACSM3 was decreased in hepatocellular carcinoma tissues." (PMID 34322485, 2021). "Acetyl-CoA medium-chain synthetase 3 (ACSM3) is a tumor suppressor in hepatocellular carcinoma (HCC)." (PMID 30390653, 2018).
liver cancer (5 papers, 2020 to 2026). An epithelial or non-epithelial malignant neoplasm that arises from the liver. "Decreased ACSM3 expression is indicative of deregulated fatty acid oxidation and a poor survival in liver cancer." (PMID 38965225, 2024). "Furthermore, ACSM3 has been reported to co-related with poor prognosis in malignant melanoma and liver cancer." (PMID 33869039, 2021).
Hypertension (4 papers, 2016 to 2024). The presence of chronic increased pressure in the systemic arterial system. "A potential role of ACSM3 in MetS is further supported by associations of ACSM3 polymorphisms with obesity, hypertriglyceridemia, and hypertension in patient cohorts." (PMID 38263332, 2024). "None of the studies, to the best of our knowledge, reported an absence of Acsm3 expression in the liver in connection with MetS, and Acsm3-deficient mice were only studied regarding hypertension." (PMID 33923085, 2021). "Finally, we explored the possibility that the ACSM3 missense variant is a genetic risk factor for diabetes and related phenotypes (e.g. hypertension) in the four individuals." (PMID 38444585, 2024). "ACSM3 (acyl-CoA synthetase medium chain family member 3) is highly expressed in the liver and kidneys and was identified as a candidate gene that may contribute to hypertension in rats and humans." (PMID 38444585, 2024). "Interestingly, Acsm3 was previously identified as a candidate gene for hypertension and other MetS traits as part of the SAH (spontaneously hypertensive rat-clone A-hypertension associated, together with Acsm2 and Acsm1), but the association with hypertension was not confirmed." (PMID 33923085, 2021).
Obesity (4 papers, 2018 to 2024). Accumulation of substantial excess body fat. "Even though most of these association studies with ACSM3 as a candidate gene used less stringent statistical criteria compared to GWAS, these results are reproducible and provide compelling evidence for ACSM3 gene involvement in obesity and hypertriglyceridemia." (PMID 33923085, 2021).
melanoma (3 papers, 2021 to 2023). A malignant, usually aggressive tumor composed of atypical, neoplastic melanocytes. "There was a positive association between ACSM3 and CD8 + T cells, macrophages, T regulatory cells, and dendritic cells in melanoma." (PMID 34322485, 2021). "In addition, krüppel-like factor 10 can upregulate ACSM3 via the PI3K/Akt signaling pathway to inhibit the malignant progression of melanoma." (PMID 37426827, 2023).
metabolic syndrome (3 papers, 2024). A cluster of metabolic risk factors for CARDIOVASCULAR DISEASES and TYPE 2 DIABETES MELLITUS. "This study establishes loss of acyl-coenzyme A synthetase (ACSM3), a mitochondrial lipid metabolism enzyme in the liver, as a cause for metabolic syndrome and related deleterious signaling." (PMID 38191811, 2024). "Additionally, the authors identified deleterious downstream p38-MAPK signalling as a targetable feature of ACSM3 deficiency that may help to ameliorate metabolic syndrome." (PMID 38263332, 2024). "In mice, diet-induced metabolic syndrome also resulted in the repression of Acsm3 gene expression in peripheral blood." (PMID 38263332, 2024). "The mitochondrial fatty acid metabolism enzyme acyl-CoA synthetase medium-chain family member 3 (ACSM3) was identified to be significantly lower expressed in the peripheral blood of metabolic syndrome patients." (PMID 38191811, 2024). "ACSM3, a mitochondrial lipid metabolism enzyme in the liver, is significantly reduced in patients with metabolic syndrome, and systemic or liver-specific depletion of Acsm3 in mice results in metabolic syndrome." (PMID 39280009, 2024). "In line, hepatic ACSM3 expression was decreased in mice with metabolic syndrome." (PMID 38191811, 2024).
serous ovarian carcinoma (3 papers, 2023 to 2024). "In high-grade serous ovarian carcinoma, ACSM3 exerts its anti-tumor effects by suppressing the activation of AMPK, leading to a reduction in mitochondrial respiration and glycolysis." (PMID 38279987, 2024). "ACSM3 also has been reported to suppresses the pathogenesis of high-grade serous ovarian carcinoma via promoting AMPK activity." (PMID 37426827, 2023). "However, it is worth noting that ACSM3 has demonstrated tumor-immunosuppressive properties in high-grade serous ovarian cancer, and ENPP7 activity has been relatively low in diseases with an increased risk of liver tumorigenesis." (PMID 38254162, 2024).
breast carcinoma (2 papers, 2022 to 2026). "For ACSM3, ECH1, and SUCLG1, no prior association with breast cancer has been reported." (PMID 41517855, 2026).
cutaneous melanoma (2 papers, 2020 to 2021). A primary melanoma arising from atypical melanocytes in the skin. "ACSM3 was reported to have a down-regulated expression in cutaneous melanoma and Duchenne muscular dystrophy." (PMID 33869039, 2021).
hypertriglyceridemia (2 papers, 2021 to 2024). A laboratory test result indicating elevated triglyceride concentration in the blood. "PD strain displays significant downregulation of three acyl-CoA-generating enzymes (ACSM3, ACSM2A, ACSL5), which can contribute to the lower ability to utilize fatty acids and hypertriglyceridemia in this strain." (PMID 33923085, 2021). "The fact that Acsm3 is not expressed in the liver of PD rats fed both control and HFD suggests the possibility of primary genetic effects of the Acsm3 PD variant on hypertriglyceridemia, the limitation being that we do not have a complete transcriptomic profile of unchallenged PD." (PMID 33923085, 2021).
Insulin resistance (2 papers, 2023 to 2024). Increased resistance towards insulin, that is, diminished effectiveness of insulin in reducing blood glucose levels. "Overall, Acsm3 KO mice presented a more severe MetS than wild-type animals, displaying impairment of glucose homeostasis, increased insulin resistance, and higher levels of serum and hepatic total cholesterol and triglycerides, NEFA, HDL, and LDL." (PMID 38263332, 2024). "Corroborating this idea, the treatment of FF-fed Acsm3 KO mice with Adezmapimod resulted in an overall improvement in glucose metabolism, reduction of insulin resistance, diminished hepatic lipid deposition, and ballooning degeneration." (PMID 38263332, 2024). "Serpine 1, an adipokine in thrombosis and insulin resistance regulation, was substantially upregulated, and genes involved in lipid metabolism, including Slc27a2, Acsm3, Acot1, and Ucp3, were dramatically decreased in BAT of BMRKO-HFD mice." (PMID 37734559, 2023).
ovarian carcinoma (2 papers, 2021 to 2025). A malignant neoplasm originating from the surface ovarian epithelium. "The results suggested that ACSM3 inhibited the growth of ovarian cancer tumors in vivo via the abrogation of the Integrin β1/AKT signaling axis." (PMID 33869039, 2021). "We artificially regulated the expression of ACSM3 to evaluate its effects on ovarian cancer malignant phenotypes." (PMID 33869039, 2021). "In this work, we found that the expression of ACSM3 was down-regulated in ovarian cancer tissues than normal tissues." (PMID 33869039, 2021). "Our results suggested the possibility that ACSM3 attenuated the expression of cell proliferation or metastasis-related proteins by the inhibition of the Integrin β1/AKT signaling pathway in ovarian cancer." (PMID 33869039, 2021). "This work aimed to explore the effects and regulatory mechanism of Acyl-CoA medium-chain synthetase-3 (ACSM3, a subunit of CoA ligases) in ovarian cancer progression." (PMID 33869039, 2021). "In this research, we artificially regulated the expression of ACSM3 to determine the effects it on the progression of ovarian cancer in vitro or in vivo." (PMID 33869039, 2021). "We artificially regulated the expression of ACSM3 to evaluate the effects on ovarian cancer progression." (PMID 33869039, 2021). "Our data revealed that the overexpression of ACSM3 inhibited cell proliferation, migration, and invasion in ovarian cancer mediated by the suppression of the Integrin β1/AKT signaling pathway in vitro." (PMID 33869039, 2021). "In this study, we found that the expression of ACSM3 was down-regulated in ovarian cancer by bioinformatics analysis, and the patients with low expression of ACSM3 showed poor overall survival." (PMID 33869039, 2021). "The overexpression of ACSM3 inhibits the malignant phenotypes via the Integrin β1/AKT signaling axis in ovarian cancer." (PMID 33869039, 2021). "In this work, we found that the expression of ACSM3 was down-regulated in ovarian cancer by bioinformatics analysis, and the patients with low expression of ACSM3 showed poor overall survival." (PMID 33869039, 2021). "While the knockdown of ACSM3 enhanced the ovarian cancer progression via the activity of the Integrin β1/AKT signaling axis." (PMID 33869039, 2021). "Our data revealed that the overexpression of ACSM3 inhibited cell proliferation, migration, and invasion of ovarian cancer cells." (PMID 33869039, 2021). "We determined the protein expression of ACSM3 in ovarian epithelial cells and ovarian cancer cells: OV-90, SK-OV-3, OVCAR-3, and A2780 cells." (PMID 33869039, 2021). "In summary, ACSM3 acts as a tumor suppressor gene and may be a potential therapeutic target of ovarian cancer." (PMID 33869039, 2021). "Conversely, ACSM3 interference facilitated the growth of tumors in ovarian cancer." (PMID 33869039, 2021). "In addition, ACSM3 also has significant value in ovarian cancer." (PMID 41430255, 2025). "Furthermore, we determined the mechanism that ACSM3 acted as an antioncogene in ovarian cancer." (PMID 33869039, 2021). "The survival analysis from the public database showed that the low level of ACSM3 is significantly correlated with the poor overall survival of ovarian cancer, thus, we have reasons to speculate that the ACSM3 is related to the clinic malignancy grade of ovarian cancer." (PMID 33869039, 2021). "Our bioinformatics analysis suggested that the expression of ACSM3 was down-regulated in ovarian cancer tissues, and the low expression level of ACSM3 might related with poorer overall survival than high mRNA expression of ACSM3 in ovarian cancer patients." (PMID 33869039, 2021). "Here, we found that the overexpressed ACSM3 blocked the expression of Integrin β1 and p-AKT, leading to the down-regulation of cyclin D1, c-Myc, Vimentin and the up-regulation of E-cadherin in ovarian cancer cells." (PMID 33869039, 2021). "Furthermore, ACSM3 could be a potential therapeutic target in ovarian cancer." (PMID 33869039, 2021).
ovarian carcinoma (continued). "However, there have been no studies on the expression of ACSM3 in ovarian cancer." (PMID 33869039, 2021). "However, the effects of ACSM3 on ovarian cancer has not been reported." (PMID 33869039, 2021).
diabetes (1 paper, 2024). "Nevertheless, we cannot rule out the possibility that the ACSM3 variant is a genetic risk factor for diabetes in the individuals in our study." (PMID 38444585, 2024).
hyperchylomicronemia (1 paper, 2021). "An absence of ACSM3 in PD can thus decrease the rate of fatty acid utilization by the liver, resulting in hyperchylomicronemia." (PMID 33923085, 2021).
Impaired glucose tolerance (1 paper, 2024). An abnormal resistance to glucose, i.e., a reduction in the ability to maintain glucose levels in the blood stream within normal limits following oral or intravenous administration of glucose. "After hepatic Acsm3 deficiency, the mice exhibited impaired glucose tolerance and insulin tolerance and increased HOMA-IR indexes (Fig. EV3D–G)." (PMID 38191811, 2024).
left ventricular hypertrophy (1 paper, 2014). Enlargement of the LEFT VENTRICLE of the heart. "New discoveries include gene-based association of NSF with triglyceride levels and several genes (ACSM3, ERI2, IL18RAP, IL23RAP and NRG1) with left ventricular hypertrophy phenotypes." (PMID 25329069, 2014).
metastatic tumour (1 paper, 2016). "Six genes were associated with tumour pathologic PT and tumour stage; among these, high expression of INTS8 and UBAP2L, and low expression of ACSM3, FCN2, LCAT, and MT1G, was significantly associated with metastatic tumour and late stage (P ≤ 0.05)." (PMID 27567667, 2016).
ovarian tumor (1 paper, 2023). "However, detailed molecular mechanisms underlying ovarian tumor-suppressive effects of ACSM3 need further investigation." (PMID 37256178, 2023).
prostate carcinoma (1 paper, 2025). A carcinoma that arises from epithelial cells of the prostate gland. "ACSM3 catalyzes the initiation of lipogenesis by producing acyl‐CoA and has been identified as supporting the growth of prostate cancer cells by protecting against ferroptosis." (PMID 39811936, 2025).
tumor (14 papers, 2013 to 2025). "However, ACSM3, which belongs to the same family, has been found to be associated with tumor progression." (PMID 37426827, 2023). "Targeting ACSM3 resulted in reduced tumor growth, revealing a link between AR and lipid metabolism, and future development of drugs targeting ACSM1 and ACSM3 is expected to explore new therapies in combination with traditional ADT therapy." (PMID 41281744, 2025). "For example, it has been shown that AR can directly regulate acyl-CoA synthetase medium-chain family members 1 and 3 (ACSM1 and ACSM3), both of which are up-regulated in tumor tissues." (PMID 41281744, 2025). "Compared to Lv-Vector, the overexpression of ACSM3 significantly ameliorated the average tumor volume." (PMID 33869039, 2021). "Expression of an AKT construct blocked the tumor suppressor effects mediated by ACSM3, making it possible that the AKT-WNK1 axis promotes cell migration and invasion in HCC." (PMID 30390653, 2018). "ECI2, PPT2, ACSM3, PMVK, and IDO1 were low expressed in the prognosis of high-risk patients, which may be tumor suppressor factors." (PMID 37256178, 2023). "Mice xenografts were then conducted to measure the effects of ACSM3 on tumor development in vivo." (PMID 33869039, 2021). "ACSM3 hold promise as a novel tumor marker and therapeutic target." (PMID 33046979, 2020). "However, compared to Lv-shRNA-NC, ACSM3 interference markedly increased the average tumor volume." (PMID 33869039, 2021). "Compared with normal tissues, six proteins (GALNT6A, FOXO1, ACSM3, DNAJA1, PRDX5, and SERPINB9) were notably overexpressed in tumour tissues." (PMID 39030559, 2024). "TENM4 and ACSM3, as well as CADPS and SLC35F3, were highly expressed in clusters 5 and 13, respectively, which represented two different sub-clusters in the tumor–stroma interface area." (PMID 38473208, 2024). "ACSM3 expression levels show no distinct differences across different tumor stages, but its expression significantly increases in metastatic cases." (PMID 38279987, 2024). "In tumor cells, ACSM3 mRNA was upregulated by HNF4α, downregulated by PPAR-γ, there was a negative feedback loop between ACSM3 and AKT, and ACSM3 expression correlated with fatty acid beta oxidation." (PMID 33923085, 2021).
cancer (2 papers, 2020 to 2025). A tumor composed of atypical neoplastic, often pleomorphic cells that invade other tissues. "As ASCM3 was associated with cancer immunity, we then examined relations between expressions of ACSM3 and immune checkpoints." (PMID 33046979, 2020). "We found ACSM3 was differentially expressed in MM, showing significant loss in cancer tissue." (PMID 33046979, 2020). "Currently there has been a dearth of studies focusing on ACSM3 in cancer." (PMID 33046979, 2020).
metabolic disorder (2 papers, 2022 to 2024). "We determined that lauric acid was the specific FA catalyzed by Acsm3, and the mitochondrial dysfunction and metabolic disorders caused by Acsm3 were attributed to its induced activation of the lauric acid/Hnf4α/p38 MAPK pathway." (PMID 38191811, 2024). "The p38 MAPK inhibitor adezmapimod could rescue the metabolic disorders caused by Acsm3 deficiency." (PMID 38191811, 2024). "Thus, we hypothesized that ACSM3 is involved in metabolic disorders and may serve as a therapeutic target of MetS." (PMID 38191811, 2024).
ACSM3 also shares sentences with these, for which no sentence is quoted: acute kidney injury (1 paper); acute myeloid leukemia (1); alcohol abuse (1); cholestasis (1); chronic kidney disease (1); Cirrhosis (1); Duchenne muscular dystrophy (1); glomerulonephritis (1); laryngeal carcinoma (1); lipid metabolism disorders (1); liver diseases (1); liver fibrosis (1); lupus nephritis (1); renal fibrosis (1); type 2 diabetes (1); vitiligo (1).